FYN (FYN proto-oncogene, Src family tyrosine kinase)
Diseases named in the same sentence as FYN in open-access papers (continued):
Sharing a sentence is not in itself a finding about the gene and the disease.
Hyperglycemia (1 paper, 2025). An increased concentration of glucose in the blood. "FYN interacts with proteins like nephrin and paxillin during hyperglycemia and impacts cytoskeleton and cell adhesion in podocytes." (PMID 41011980, 2025).
Infertility (1 paper, 2022). "Specifically, triple knockouts of SRC, YES, and FYN result in embryonic lethality, double knockouts of SRC and YES, or SRC and FYN, result in perinatal lethality, and a single knockout of SRC causes postnatal lethality or infertility, but a single knockout of YES or FYN is viable and fertile." (PMID 36016954, 2022).
intrahepatic cholangiocarcinoma (1 paper, 2016). A carcinoma that arises from the intrahepatic bile duct epithelium in any site of the intrahepatic biliary tree.
Intraventricular hemorrhage (1 paper, 2019). Bleeding into the ventricles of the brain. "Transient inhibition of SFK family member FYN improved cognitive function after intraventricular hemorrhage or intraventricular thrombin injection in a rat model." (PMID 30836997, 2019).
invasive carcinoma (1 paper, 2015). A carcinoma that is not confined to the epithelium, and has spread to the surrounding stroma. "Tumor progression to invasive carcinoma is associated with activation of SRC family kinase (SRC, YES, FYN) activity and loss of cellular cohesion." (PMID 26549256, 2015).
lupus nephritis (1 paper, 2021). Glomerulonephritis in the context of systemic lupus erythematosus. "Regarding passive immunotherapeutic strategies such as ICI, FYN-activating signatures have been associated with lupus nephritis, an autoimmune condition, loosely suggesting that increased FYN activity might increase the risk of autoimmune complications following ICI." (PMID 34012443, 2021).
mast cell neoplasm (1 paper, 2018). A heterogeneous group of disorders characterized by the abnormal growth and accumulation of mast cells in one or more organ systems. "In conclusion, the present study showed that AQ1 G4-binding compound inhibited KIT expression and its downstream signaling molecules GRB2, AKT and FYN in two in vitro models of human and canine mast cell neoplasms (HMC1.2 and C2 cells)." (PMID 30459395, 2018).
muscular atrophy (1 paper, 2024). The loss of muscle tissue due to inactivity or disease. "One of the mechanisms of up-regulated FYN, which could account for the DMD phenotype is that the Fyn-tyrosine kinase activates the mammalian target of rapamycin 1 (mTORC1) signaling complex, which inhibits macroautophagy and induces marked muscular atrophy." (PMID 38762732, 2024).
myeloma (1 paper, 2025). "This antibody binds to SLAMF7 on myeloma cells, simultaneously activating NK cells and macrophages through the SLAMF7-EAT2 interaction and stimulating the FYN/Syk-PI3K-Akt/mTOR signaling pathway." (PMID 40646691, 2025).
osteoarthritis (1 paper, 2022). A noninflammatory degenerative joint disease occurring chiefly in older persons, characterized by degeneration of the articular cartilage, hypertrophy of bone at the margins and changes in the synovial membrane. "FYN has been reported to promote osteoarthritis by activating the β-catenin pathway; nevertheless, its role in the development of AS has yet to be determined." (PMID 34986893, 2022).
ovarian tumors (1 paper, 2023). "There is negative reciprocal regulation between SMAD4 and FYN in ovarian tumors, and knockdown of SMAD4 results in elevated levels of FYN expression, and FYN activation leads to dissociation of cell-cell junctions and adhesion, resulting in increased tumor metastasis." (PMID 36740671, 2023).
periodontitis (1 paper, 2021). An acute or chronic inflammatory process that affects the tissues that surround and support the teeth. "This means that FYN, LYN and LCK, which are highly expressed, play an important role in the imbalance of the immune system of periodontitis." (PMID 33841510, 2021).
peripheral T-cell lymphomas (1 paper, 2016). "Recently, FYN mutations were found in peripheral T-cell lymphomas where they impaired DNA damage response and escape from immune surveillance." (PMID 27566560, 2016).
prostate intraepithelial neoplasia (1 paper, 2014). A neoplastic proliferation of the epithelial cells that line the acini and the ducts of the prostate gland. "Further, studies have shown through a combination of data mining, immunobloting, RT-PCR, and immunohistochemistry that FYN expression is upregulated in the progression to cancer from both normal epithelium and prostate intraepithelial neoplasia (PIN)." (PMID 24970799, 2014).
rectal tumors (1 paper, 2020). "Moreover, high expression levels of PAI1 are associated with increased metastasis and invasion of rectal tumors in this cohort and TCGA database, respectively, which is correlated with EMT-associated and drug target genes expression, including PDGFRa, PDGFRb, FYN, PIM1 and BRAF." (PMID 32344898, 2020).
Stroke (1 paper, 2022). Sudden impairment of blood flow to a part of the brain due to occlusion or rupture of an artery to the brain. "FYN is shown to interact with NMDAR during the ischemic response and phosphorylation of several proteins, which is implicated in cell death in stroke via reactive oxygen species generation and calcium flux." (PMID 35250546, 2022).
systemic inflammatory response syndrome (1 paper, 2024). SIRS is a serious condition related to systemic inflammation, organ dysfunction, and organ failure. "The results of a meta-analysis suggested that FYN could contribute to patient prognosis and that CD247 could be used to distinguish between patients with sepsis and patients with systemic inflammatory response syndrome (SIRS)." (PMID 38716051, 2024).
T-cell lymphoma (1 paper, 2021). "For T-cell lymphoma six genes are found in cosmic (JAK1, PLCG1, FYN, ARID1A, EP300, and MAP3K1), and 13 are known oncogenes." (PMID 34570764, 2021).
tauopathy (1 paper, 2024). Neurodegenerative disorders involving deposition of abnormal tau protein isoforms (tau proteins) in neurons and glial cells in the brain. "As a positive control, we transfected cells with FYN, which phosphorylates tau at Tyr18 residue and promotes tau aggregation in a tauopathy mouse model." (PMID 39528671, 2024).
tuberculosis (1 paper, 2020). A chronic, recurrent infection caused by the bacterium Mycobacterium tuberculosis. "In the GSE20050, we found that when compared with normal lung parenchyma, LRRK2 was significantly down-regulated in caseous tuberculosis granulomas (p = 0.0361), but CCR7 and FYN was upregulated (p = 0.0024 and p = 0.0486, respectively)." (PMID 32987825, 2020).
viral myocarditis (1 paper, 2009). Myocarditis that is caused by an infection with a viral agent. "The database not only identified the relationship of the "FYN" gene to Giant Cell Myocarditis but also to Viral Myocarditis which would have otherwise been considered "not known"." (PMID 19208197, 2009).
cancer (74 papers, 2011 to 2025). A tumor composed of atypical neoplastic, often pleomorphic cells that invade other tissues. "This is a contentious finding because FYN encodes a Src family protein kinase known to induce anti-apoptotic signaling in many cancers by dysregulation of Ak strain transforming (AKT) activity." (PMID 40296913, 2025). "Upregulation of FYN is a general feature of drug-tolerant cancer cells, suggesting the association of FYN expression with drug resistance and tumor recurrence after treatment." (PMID 40243589, 2025). "Expression of FYN, a member of Src family kinase, has been implicated in cancer malignancy including drug resistance." (PMID 40243589, 2025). "A TCGA cancer database analysis based on genes related to lipid metabolism in colon adenocarcinoma found that FYN gene expression was associated with the activation of the EMT pathway." (PMID 36740671, 2023). "The result showed that most of these genes were associated with prognosis significantly in pan-cancer, and FYN was associated with prognosis significantly in 10 of 16 cancers." (PMID 36945884, 2023). "FYN encodes a membrane-associated tyrosine kinase that promoted cell proliferation, migration and invasion and inhibited apoptosis of cancer cells." (PMID 36092919, 2022). "Recent studies have demonstrated the importance of FYN in the resistance or susceptibility of cancer cells to pharmacological intervention." (PMID 33207722, 2020). "KDM3A transcriptome analysis revealed, in addition to Ets1 and MCAM, other genes previously implicated in the promotion of aggressive cancer properties, including the genes FYN, AXL, LOXL2 and PLAU." (PMID 32577157, 2020). "ADD2 encodes a cytoskeletal protein that interacts with FYN, a tyrosine kinase promoting cancer cell migration." (PMID 23046790, 2012). "In the current study, we retrieved TCGA-GC data for analysis and found that FYN mRNA was highly expressed in GC tissues and was closely associated with common cancer-promoting signaling pathways, and patients with high FYN expression had significantly shorter OS and PFS." (PMID 37016377, 2023). "Moreover, eleven kinases were cancer-associated, some of which include FYN proto-oncogene tyrosine kinase (FYN), aurora kinase B (AURKB), and integrin-linked kinase (ILK)." (PMID 33499132, 2021). "Additionally, several studies have demonstrated that FYN functions as a promoter in diverse cancers and is associated with a poor prognosis." (PMID 31285693, 2019). "Also, the impact of LYN and FYN on NSCLC patients’ survival may be linked to their ability to regulate biological process associated with cancer progression, such as resistance to apoptosis and metastasis." (PMID 29937990, 2018). "Given the regulatory role of FYN in cancer promotion by way of AKT, AKT inhibition presents a viable anti-tumor strategy." (PMID 39934141, 2025). "As a member of the Src family protein kinases, FYN is a well‐defined cancer‐related gene that promotes cancer growth and metastasis through diverse biological functions, including cell growth, migration, apoptosis and epithelial‐to‐mesenchymal transition." (PMID 40741875, 2025). "In contrast, sgRNAs targeting the src family tyrosine kinase FYN were depleted, as expected from its role in cancer cell immune editing." (PMID 38228372, 2024). "Super-enhancers have been found in genes involved in T-cell activation (IL2RA/CD25, CD30, and FYN) and known cancer genes (TP73, CCR4, TIAM2, NFATC1, NFATC2, and PIK3R1) in ATL cells." (PMID 38791169, 2024). "Suppression of FYN activity, thus, holds the potential to improve prognosis and extend patient survival in various cancer types." (PMID 39479685, 2024). "While FYN is known to promote cellular proliferation and migration in multiple types of cancer, our findings reveal that SS18-SSX exerts a negative effect on FYN expression, at least in part, by repressing FYN transcription." (PMID 39045458, 2024).
cancer (continued). "FYN is highly expressed in many cancers and promotes cancer growth and metastasis through diverse biological functions such as cell growth, apoptosis, and motility migration, as well as the development of drug resistance in many tumors." (PMID 38334632, 2024). "Using The Cancer Genome Atlas dataset, a 5-CD8Gs risk model (KLRB1, FYN, IL2RG, FCER1G, and DGKZ) was constructed, which was verified in International Cancer Genome Consortium and gene expression omnibus datasets." (PMID 38489709, 2024). "The emergence of drug resistance remains a formidable challenge for the effective treatment of cancer patients, and several studies have found that FYN promotes drug resistance in tumors." (PMID 36740671, 2023). "The function of FYN as a protein kinase in cancer is regulated by protein levels and its activity, and this section will focus on its upstream regulatory molecules." (PMID 36740671, 2023). "Recent research on the FYN gene has revealed its involvement in cancer progression, metastasis, and drug resistance." (PMID 37324495, 2023). "A proto-oncogene from the Src family called FYN has been found in several investigations to increase cancer cell proliferation and prevent apoptosis." (PMID 37324495, 2023). "The use of FYN inhibitors in patients with high expression or elevated FYN activity will help improve survival rates in cancer patients." (PMID 36740671, 2023). "To further verify the expression of FYN in GC and its impact on the prognosis in GC patients, we collected immunohistochemical analysis of cancer and paracancerous tissue specimens from 54 GC patients." (PMID 37016377, 2023). "FYN is a proto-oncogene belonging to the Src family, which has been reported in many studies to promote cancer cell proliferation and inhibit apoptosis." (PMID 36740671, 2023). "According to this study, DNA methylation level of FYN in the promoter region decreased in 13 cancers and significantly regulated transcription downstream of the gene." (PMID 36945884, 2023). "Several compounds have been shown to inhibit the kinase activity of FYN in cancer and have also shown to be of great value in cancer therapy." (PMID 36740671, 2023). "The results of clinical samples show that TOPK and p-TOPK are expressed at elevated levels in GC, patients with high expression of TOPK and p-TOPK have shorter survival, and TOPK as a downstream molecule of FYN is also a cancer-promoting factor in GC." (PMID 37016377, 2023). "SHP2 facilitates the localization and activation of FYN downstream of alpha6beta4 integrin to promote cancer invasion." (PMID 36740671, 2023). "FYN is a protein tyrosine kinase involved intracellular signalling cascades in T-cells and neurons, cell growth, fertilization, mitosis, development and cancer." (PMID 36141481, 2022). "FYN knockdown significantly decreased cancer cell migration and invasion, whereas FYN overexpression increased cancer migration and invasion." (PMID 36498797, 2022). "FYN gene also plays an important role in the process of cancer development, including regulation of cell growth and survival, cell adhesion, cell signaling, cell motility, and immune response." (PMID 36713541, 2022). "FYN overexpression promotes cell proliferation and cell migration in various types of cancers and mediates epithelial–mesenchymal transition." (PMID 35453806, 2022). "Of all of the other family members (FYN, YES, BLK, YRK, FGR, HCK, LCK, and LYN) cSrc is the most often associated with cancer progression." (PMID 33841333, 2021). "The known roles of VEGFA, ACKR3, IL6 and FYN establish them as the major regulators of cancer pathways cluster in the network." (PMID 34439877, 2021). "Many of these significantly increased proteins encoded on autosomes, such as ERK2, FYN, and CDK6, are linked to cancer and other diseases." (PMID 33910018, 2021).
cancer (continued). "Considering the top drugs able to modulate the predicted candidate genes, both Dasatinib and Ilorasertib share the same target genes (LYN, CSF1R, FYN) and are used as anti-cancer drugs." (PMID 33918694, 2021). "Fyn kinase, encoded by FYN, stimulates a wide array of oncogenic pathways including cell proliferation, migration, EMT, and therapy resistance in many cancers." (PMID 34439877, 2021). "FYN is differentially expressed in multiple cancers, and has a correction with cancer progression by controlling cellular motility, cell growth, and death." (PMID 33679866, 2020). "Mechanistic studies in other cancer models suggest inhibition of FYN leads to greater cell death in KRAS mutant cells than in KRAS wild-type cells." (PMID 33233470, 2020). "In cancer, FYN contributes to the development and progression of several cancer types through the control of cell growth, death, and motility." (PMID 33207722, 2020). "FYN is closely related to cancer development, tumor progression, and even dissemination in diverse cancers." (PMID 31285693, 2019). "Disruptions FYN signaling pathways often have implications in the formation of a variety of cancers." (PMID 27895661, 2016). "Since it has been reported that COX2 and FYN both are localized in caveolae like structures in some cancer cells, it is possible that caveolae is one of cellular comparmtent where FYN is capable to regulate COX2 activity." (PMID 24970799, 2014). "Our findings reveal that FYN is specifically upregulated at the mRNA level possibly through epigenetic regulations, providing further depth to our understanding of drug resistance in cancer therapy." (PMID 40243589, 2025). "Indeed, PP2 was shown to target both FYN and another Src family kinase, lymphocyte-specific kinase (Lck), the latter of which has the known function of promoting cancer cell proliferation and chemoresistance." (PMID 40296913, 2025). "In addition, FYN influences various cancer‐related signaling pathways, making it a promising therapeutic target for tumor treatment." (PMID 39479685, 2024). "In addition, FYN is involved in the regulation of multiple cancer-related signaling pathways, including interactions with ERK, COX-2, STAT5, MET, and AKT." (PMID 38334632, 2024). "Moreover, FYN has been identified as a potential therapeutic target for cancer treatment due to its roles in tumor cell proliferation, survival, and invasion." (PMID 37324495, 2023). "This provides strong evidence for FYN as a pro-cancer factor in GC." (PMID 37016377, 2023). "Evidence has shown that FYN plays a role in cancer pathogenesis and drug resistance." (PMID 36672292, 2023). "In the current study, several miRNAs were identified that could regulate FYN expression-mediated role in cancer." (PMID 36740671, 2023). "Current evidence indicates that FYN plays a pro-oncogenic role in cancer development." (PMID 36740671, 2023). "The highest level, FYN (Fyn Proto-Oncogene), was regulated by DNA methylation in 13 cancers." (PMID 36945884, 2023). "Ras/PI3K/Akt signaling can increase FYN overexpression in cancer, thereby promoting tumor cell migration and invasion.FYN forms a molecular complex with Nck and PAK-2 and p-Tyr molecular complexes with Nck and PAK-2 and assembles in a p-Tyr1214-dependent manner." (PMID 36740671, 2023). "FYN has been shown to promote the progression of multiple cancers including GC." (PMID 37016377, 2023). "As such, the development of new drugs targeting FYN could hold significant promise for cancer therapy." (PMID 37324495, 2023). "The pro-cancer role of FYN in multiple malignancies has been elucidated." (PMID 37016377, 2023). "Thus, FYN is highly expressed in several cancer-resistant cell and is involved in developing cancer drug resistance." (PMID 36740671, 2023).